REN (renin)
Diseases named in the same sentence as REN in open-access papers (continued):
Sharing a sentence is not in itself a finding about the gene and the disease.
primary aldosteronism (continued). "Primary aldosteronism (PA), also known as Conn syndrome, characterized by renin-independent aldosterone secretion, represents the most common cause of secondary hypertension among middle-aged adults." (PMID 38139166, 2023). "Seventeen patients exhibited hypercortisolism, 6 had elevated androgen levels, and 2 were screened positively with primary aldosteronism (PA) based on aldosterone-to-renin ratio." (PMID 36967802, 2023). "Based on these findings, the distinction between “biochemically overt primary aldosteronism” and “renin-independent aldosterone production” is arbitrary." (PMID 38075562, 2023). "More severe renal damage occurs in primary aldosteronism, and some studies have shown that the aldosterone/renin ratio (ARR) can also predict renal damage in EHT." (PMID 37848834, 2023). "The aldosterone-to-renin ratio (ARR) is the most widely used screening test for primary aldosteronism (PA) and is recommended by current guidelines." (PMID 34515895, 2023). "An aldosterone-to-renin ratio of at least 240 pg/mL per ng/mL/h and a plasma aldosterone concentration of at least 200 pg/mL are considered positive for primary aldosteronism." (PMID 35204632, 2022). "Primary aldosteronism (PA) is the most frequent form of secondary endocrine hypertension, which is characterized by excessive aldosterone secretion and suppressed renin." (PMID 36362504, 2022). "A large component of these patients, even after excluding primary aldosteronism, have a low renin phenotype, and would respond to sodium restriction and escalation of natriuresis in some form." (PMID 35268545, 2022). "Of the 33 screened patients, an elevated aldosterone-to-renin ratio was noted in 8 patients and a diagnosis of primary aldosteronism was made in 4 patients." (PMID 35195879, 2022). "The recommended screening test for primary aldosteronism based on current guidelines is measuring plasma aldosterone-renin ratio (ARR)." (PMID 35371662, 2022). "Primary aldosteronism (PA) is the most common form of secondary hypertension and is characterised by increased adrenal aldosterone secretion and suppressed renin." (PMID 35622194, 2022). "Elevated plasma aldosterone levels of 489 pg/ml (normal, 68.0–173.0 pg/ml), low plasma renin concentrations of 2.89 pg/ml (normal, 1.1–20.2 pg/ml), and elevated aldosterone renin ratios (ARRs) of 169.2 were strongly indicated primary aldosteronism." (PMID 36371163, 2022). "Determination of plasma aldosterone concentrations (PAC) and plasma active renin concentrations (ARC) is essential for the diagnosis of primary aldosteronism (PA)." (PMID 33564064, 2022). "For the detection of primary aldosteronism (PA), hypertensive patients are screened using the aldosterone-to-renin ratio (ARR)." (PMID 33679972, 2021). "Clinicians should pay attention to the ratio of visceral-to-subcutaneous fat tissue volume and encourage primary aldosteronism patients to improve their lifestyle in addition to treating renin-aldosterone activity." (PMID 34363052, 2021). "The most sensitive screening test for primary aldosteronism is the measurement of the plasma aldosterone concentration and plasma renin activity to calculate the aldosterone/renin ratio." (PMID 34926077, 2021). "In primary aldosteronism, the most common endocrine form of arterial hypertension, excess aldosterone secretion was contended to be independent from renin and Ang II as the patients with primary aldosteronism show very low levels of Ang II in plasma." (PMID 33657582, 2021). "Unsuppressed renin and lower ARR levels were associated with decreased eGFR in patients with primary aldosteronism." (PMID 32089681, 2020). "The aldosterone to renin ratio and saline infusion tests were used to diagnose primary aldosteronism." (PMID 32990741, 2020).
primary aldosteronism (continued). "In the previous retrospective study, we obtained the optimal cutoff value of aldosterone-to-renin ratio detected by chemiluminescence assay, a newly developing method, and prompted its high efficiency in primary aldosteronism screening in upright position." (PMID 32908690, 2020). "Although it has some shortcomings, chemiluminescence assay-detected aldosterone-to-renin ratio is a highly effective index for screening primary aldosteronism in practice." (PMID 32908690, 2020). "A biochemical evaluation revealed a very high aldosterone level and an undetectable renin level, both are compatible with primary aldosteronism." (PMID 32665023, 2020). "Among patients tested for primary aldosteronism, a selection of 8 steroids in combination with the aldosterone to renin ratio showed improved effectiveness for diagnosis over either strategy alone." (PMID 32990741, 2020). "Elevated aldosterone to renin ratio and unsuppressed plasma aldosterone concentration after saline infusion test suggested primary aldosteronism." (PMID 31208392, 2019). "Aldosterone-to-plasma renin activity ratio (ARR) derived from traditional radioimmunoassay (RIA) is widely used to detect primary aldosteronism (PA)." (PMID 31354984, 2019). "Much lesser elevations of circulating progesterone in the luteal phase of the menstrual cycle have been shown to raise plasma aldosterone concentrations in some women to false-positive aldosterone/renin ratios for primary aldosteronism." (PMID 28492512, 2017). "For biochemical confirmation of the clinical suspicion of primary aldosteronism, the aldosterone to renin ratio (ARR) would have to be determined." (PMID 27682153, 2016). "Patients with primary aldosteronism present with high circulating aldosterone and suppressed renin concentrations and elevated ARRs." (PMID 24612948, 2014). "Patients with primary aldosteronism are detected by raised plasma aldosterone concentration/renin activity or renin concentration ratio (PAC/PRA/or PRC ratio), together with variably raised plasma aldosterone." (PMID 22848660, 2012). "Recent recommendations suggest screening for primary aldosteronism using the aldosterone to renin ratio." (PMID 20482833, 2010). "If stimulated renin is low and the aldosterone is high, the problem is primary aldosteronism, and the best treatment is usually aldosterone antagonists (spironolactone or eplerenone; high-dose amiloride for men where eplerenone is not available)." (PMID 21532778, 2010). "Patients with low renin and high levels of aldosterone have primary aldosteronism, which accounts for 20% of resistant hypertension." (PMID 21532778, 2010). "In primary aldosteronism, the most discriminating test is the ratio of plasma aldosterone (ng/dl) to plasma renin activity (ng/ml/h); a value of greater that 30 indicates primary aldosteronism." (PMID 17647025, 2009). "Ratio of plasma aldosterone (ng/dl) to plasma renin activity (ng/ml/h) of over 30 (normal < 20) is highly suggestive of primary aldosteronism." (PMID 17647025, 2009). "With broader screening for primary aldosteronism (PA), clinicians are increasingly identifying patients with low renin levels who do not meet current diagnostic criteria for PA." (PMID 42120732, 2026). "In a typical case of primary aldosteronism, one might see a higher aldosterone level (often >20 ng/dL) with an undetectable renin." (PMID 41356982, 2025). "Its low potency, especially at low electrical activity, and its lack of selectivity may explain its failure to reduce aldosterone production, estimated as aldosterone-to-renin ratio, in a clinical study involving patients with primary aldosteronism." (PMID 40957616, 2025). "Renin measurement is key to diagnosing primary aldosteronism (PA)." (PMID 41066530, 2025).
primary aldosteronism (continued). "As such, people with a low direct renin concentration and various levels of aldosterone concentration that do not result in an aldosterone-to-renin ratio that meets the ‘positive’ screening threshold for primary aldosteronism are part of the continuum." (PMID 39026100, 2024). "The key to diagnosing licorice toxicity lies in recognizing the characteristic suppression of both aldosterone and renin levels, a profile evident in our patient, which distinguishes it from conditions like Conn’s syndrome that present with elevated aldosterone and low renin." (PMID 39498427, 2024). "Therefore, primary aldosteronism is often underdiagnosed, and every patient with RH should be screened for primary aldosteronism with the measurement of plasma renin and aldosterone levels." (PMID 39014113, 2024). "The current reports of the correlation between renin-aldosterone system activity and primary hypertension are gradually increasing, and clinical and biochemical data indicate that there is a gray area between primary hypertension, and primary aldosteronism." (PMID 38177694, 2024). "In primary aldosteronism, aldosterone is overproduced and renin activity is suppressed." (PMID 37848834, 2023). "Outside of pregnancy, primary aldosteronism is characterized by an elevated aldosterone-to-renin ratio in blood that exceeds a defined cut-off value; clear criteria for detection of aldosteronism where the renin–angiotensin system is also activated are not defined." (PMID 38001956, 2023). "Mice generated by in vitro fertilization showed elevated intracellular calcium in the aldosterone-producing zona glomerulosa, an elevated aldosterone/renin ratio, and persistently elevated serum aldosterone on a high-salt diet as signs of primary aldosteronism." (PMID 37698934, 2023). "Primary aldosteronism, a high prevalence but largely unrecognized disease, is an autonomous hypersecretion of aldosterone from the adrenal cortex, leading to an increase in plasma aldosterone concentration and suppression of renin." (PMID 38124109, 2023). "Urinary electrolytes, and renin and aldosterone levels taken at the ED ruled out primary aldosteronism and renal potassium and hydrogen loss." (PMID 36619435, 2022). "The authors hypothesized that blood pressure rise could be driven in this cohort by a renin-independent aldosterone mechanism and some of the studied patients could have unrecognized primary aldosteronism." (PMID 35627493, 2022). "According to Endocrine Society Practice Guideline, the use of this drug may reduce aldosterone and greatly increase renin, confounding the detection of a case of primary aldosteronism (secondary hypertension)." (PMID 35683380, 2022). "Determining values of plasma renin activity (PRA) or plasma active renin concentration (ARC), plasma aldosterone concentration (PAC), and aldosterone-to-renin ratio (ARR) is essential to diagnose primary aldosteronism (PA), but it takes several days with conventional radioimmunoassays (RIAs)." (PMID 34242264, 2021). "Some studies have been identified that can improve the detection of milder forms of primary aldosteronism when using less conservative ARR thresholds with suppressed renin activity and plasma aldosterone levels >9 ng/dL, which is in agreement with the outcome of this study." (PMID 34804057, 2021). "Aldosterone-to-renin ratio (ARR) is a screening tool for primary aldosteronism (PA), but the significance of ARR when the PA criteria are not met remains largely unknown." (PMID 33188272, 2020). "Plasma aldosterone-to-renin ratio (ARR) is popularly used for screening primary aldosteronism (PA)." (PMID 33256676, 2020). "In the original family with FH type II, eight individuals were carriers of the CLCN2 mutation (resulting in the CIC-2 p.Arg172Gln substitution) and of these, seven tested positive with a screening test for primary aldosteronism (elevated aldosterone-to-renin ratio)." (PMID 29642543, 2018).
primary aldosteronism (continued). "One carrier for the CIC-2 p.Arg172Gln variant had a normal aldosterone-to-renin ratio, and therefore did not have primary aldosteronism, indicating an incomplete penetrance of the allele." (PMID 29642543, 2018). "The authors therefore concluded that because the aldosterone-renin ratio was highly associated with the plasma rennin activity, this ratio was not a renin-independent diagnostic test for screening primary aldosteronism." (PMID 26979481, 2016). "Importantly, primary aldosteronism is part of a renin-independent hyperaldosteronism continuum." (PMID 39026100, 2024). "As aldosterone-renin ratio is recommended as the most reliable tool available for screening primary aldosteronism, we speculated that for moderate-severe GO patients with CAS > 3, inferior rectus/fat ratio may be a useful indicator to predict the response of GC therapy." (PMID 28845157, 2017). "In addition to renin (activity) and aldosterone levels for calculation of ARR or AARR, analysis of parathyroid hormone may be of additional diagnostic value in primary aldosteronism." (PMID 27682153, 2016). "Clinical follow-up was carried out according to primary aldosteronism surgical outcome (PASO) criteria, and included monitoring of drug type, blood pressure, serum potassium, and aldosterone/renin ratio to evaluate surgical effect." (PMID 40815389, 2026). "Medications that interfere with the renin-angiotensin-aldosterone system - particularly ACE inhibitors and mineralocorticoid receptor antagonists - can mask primary aldosteronism by altering ARR interpretation." (PMID 41356982, 2025). "We also analyzed the aldosterone/renin ratio (ARR), which is commonly used to diagnose primary aldosteronism." (PMID 40648780, 2025). "One measure of RAAS activity, the aldosterone-renin-ratio (ARR), is used to screen for primary aldosteronism." (PMID 37690031, 2023). "A decreased brachial artery flow-mediated dilation (another LEAD related parameter) was also observed among participants with high aldosterone-to-renin ratio (ARR, an indicator of subtle primary aldosteronism) when compared to individuals who had normal ARR." (PMID 38124109, 2023). "Screening for primary aldosteronism is performed by measuring plasma levels of two components of the RAAS; aldosterone and renin, and calculating the aldosterone-to-renin ratio (ARR)." (PMID 37690031, 2023). "In the PA group, the patients showed higher plasma aldosterone concentration (PAC), lower plasma renin activity (PRA), and higher plasma aldosterone to renin ratio (ARR), consistent with the diagnosis of primary aldosteronism." (PMID 35614110, 2022). "As an initial methodological evaluation, plasma renin activity results obtained by radioimmunoassay, LC/ESI-MS/MS, and immuno-MALDI on 64 samples from an outpatient primary aldosteronism screening program have been compared." (PMID 24359218, 2013). "Given the fundamentally different mechanisms of renin and aldosterone regulation in primary aldosteronism and PHA-1, it is reasonable that ARR did not prove useful for the diagnosis of PHA-1 in the present study." (PMID 40648780, 2025). "Secondary aldosteronism (SA) is distinguished from primary aldosteronism through renin – SA is characterised by high aldosterone and high or non-suppressed renin levels." (PMID 40093086, 2025). "An ARR of 36 is above the usual screening cutoff for primary aldosteronism, although the plasma aldosterone level of 16 ng/dL is only modestly elevated and the renin, while low, is not fully suppressed." (PMID 41356982, 2025). "In primary aldosteronism, excessive aldosterone secretion enhances sodium reabsorption, raises blood pressure, and suppresses renin release via negative feedback." (PMID 40648780, 2025). "In primary aldosteronism, aldosterone excess is relatively independent of the renin-angiotensin system and only weakly suppressed by sodium loading." (PMID 38425104, 2024).
primary aldosteronism (continued). "Primary aldosteronism (PA) is distinguished by aldosterone synthesis, which is independent of the renin-angiotensin system." (PMID 39518893, 2024). "In primary aldosteronism, excess aldosterone results in negative feedback and suppressed renin concentration, whereas in secondary aldosteronism, excess activation of the RAAS results in higher renin and a concomitant increase in aldosterone." (PMID 37690031, 2023). "Firstly, we did not measure aldosterone or renin in UK Biobank, and screening or confirmatory tests for primary aldosteronism was hardly conducted." (PMID 38124109, 2023). "Examples include the use of renin-angiotensin-aldosterone inhibitors in coronavirus disease 2019 (COVID-19) patients, the landmark Systolic Blood Pressure Intervention Trial (SPRINT), management of resistant hypertension, and primary aldosteronism." (PMID 35371662, 2022). "Primary aldosteronism (PA) usually accompanies suppressed plasma renin activity (PRA) through a negative feedback mechanism." (PMID 35482752, 2022). "While in several patients various alterations of renin and/or aldosterone levels were detected, no suspicion of primary aldosteronism or zona glomerulosa insufficiency was present." (PMID 34751898, 2022). "Primary aldosteronism is characterized by aldosterone concentrations that are inappropriately high in relation to renin and that are not adequately suppressible by sodium loading, which would normally reduce aldosterone secretion." (PMID 27682153, 2016). "Clinical features can suggest the diagnosis but are not specific, but Conn’s syndrome is suspected in presence of diastolic hypertension, low plasma renin and high plasma aldosterone not able to be suppressed by fluid challenge." (PMID 25368694, 2015). "ARB’s (and probably aliskiren) are particularly effective at suppressing aldosterone production, so a patient with a low or low-normal renin level and a high or high-normal aldosterone level while taking an ARB probably has primary aldosteronism, for the purposes of adjusting medical therapy." (PMID 21532778, 2010). "Similarly, plasmatic or urinary metanephrines and the assessment of the plasma aldosterone/renin activity ratio are crucial to rule out the presence of pheochromocytoma and primary aldosteronism, respectively." (PMID 40940994, 2025). "Additionally for our patient, elevation of both plasma renin activity and aldosterone was not consistent with a diagnosis of primary aldosteronism." (PMID 40704299, 2025). "Subclinical primary aldosteronism (PA), defined as a condition with elevated ARR or suppressed renin but which does not meet the full diagnostic criteria for PA, has been reported in older adults who are more likely to suffer from more severe cardiovascular complications compared to young adults." (PMID 40863169, 2025). "Subsequently, positive results of the captopril challenge test based on radioimmunoassay turned into “negative” based on the novel assay in 45% patients with primary aldosteronism, using the conventional cut-off value (aldosterone-to-renin activity ratio > 20 ng/dL per ng/mL/h)." (PMID 38454147, 2024). "For diagnosis of hypertensive cases due to other diseases, i.e. renal artery stenosis and primary aldosteronism, the ratio between aldosterone to renin is preferred to determination of plasma renin concentration, as renin levels without aldosterone are difficult to interpret." (PMID 33857767, 2021). "During hospitalization for the diagnosis and subtyping of primary aldosteronism, patients were treated with drugs that have minimal influence on the renin–angiotensin–aldosterone system, such as non-dihydropyridine calcium-channel blockers, α-blockers, or direct vasodilators." (PMID 34867814, 2021).